PAX9 (paired box 9)
Diseases named in the same sentence as PAX9 in open-access papers (continued):
Sharing a sentence is not in itself a finding about the gene and the disease.
cleft lip (3 papers, 2014 to 2021). Congenital defect in the upper lip where the maxillary prominence fails to merge with the merged medial nasal prominences. "Mice models have shown that PAX9 gene deletion and downregulation of PAX9 causes the formation of cleft secondary palate and associations have been found with PAX9 and the development of cleft lip in mice." (PMID 34684112, 2021). "The Mann–Whitney U test indicated a statistically significant difference for the number of PAX9-positive epitheliocytes in the surface epithelium between the control group and the bilateral cleft lip affected tissue group (U = 13.5, p = 0.012)." (PMID 34684112, 2021). "The median number of PAX9-positive cells within the epithelium of bilateral cleft lip patient group tissue was a few (+) positive cells and ranged from no positive epitheliocytes to moderate to numerous (++/+++) positive epitheliocytes." (PMID 34684112, 2021). "The median number of PAX9-positive connective tissue cells such as fibroblasts, macrophages, and endothelial cells within the connective tissue of the unilateral cleft lip patient group was moderate (++) and ranged from no positive cells to numerous (+++) positive cells." (PMID 34684112, 2021).
oral squamous cell carcinoma (3 papers, 2017 to 2024). "PAX9 is one of the nine members of "paired box” (PAX)-containing transcription factor family and its inhibition has been shown to induce apoptosis with increased cleavage of caspase-3 and PARP, increased expression of BAX and decreased expression of BCL-2 in oral squamous cell carcinoma." (PMID 28572861, 2017).
cervical cancer (2 papers, 2022 to 2024). A primary or metastatic malignant neoplasm involving the cervix. "In cervical cancer cell lines (C-33A, CaSKi, HeLa, SiHa), the expression level of PAX9 was lower than that in normal cells (HCerEpiC)." (PMID 35628401, 2022). "PAX9 expression in cervical cancer tissue was lower than that in the adjacent normal tissues." (PMID 35628401, 2022).
lung adenocarcinoma (2 papers, 2020 to 2025). A carcinoma that arises from the lung and is characterized by the presence of malignant glandular epithelial cells. "Concerning the oncogenic role of PAX9, an up-regulation of mRNA and protein levels have been detected in lung adenocarcinoma (LUAD) tissues and cell lines (A549 and H-1299) compared to healthy counterparts." (PMID 40506992, 2025). "By integrating the copy number information, we identified that four of above defined 129 upregulated eRNAs targeting FOXO6, TERT and PAX9 were activated by CNA in lung adenocarcinoma samples." (PMID 33042282, 2020).
melanoma (2 papers, 2017 to 2019). A malignant, usually aggressive tumor composed of atypical, neoplastic melanocytes. "Moreover, as previous study reported that PAX9 is down-regulated and miR-301a, 223 is up-regulated in human melanoma." (PMID 31569419, 2019). "We found, PAX9 and NDRG2, which were down-regulated in human and mouse melanoma, also were down-regulated in COM." (PMID 31569419, 2019). "Our qPCR results showed significant down-regulation of PAX9, NDRG2, and ACVR2a in melanoma compared with normal, and the relative expression of the respective miRNA–mRNA pairs showed significant negative correlation." (PMID 31569419, 2019).
ovarian carcinoma (2 papers, 2021 to 2022). A malignant neoplasm originating from the surface ovarian epithelium. "We therefore explored the expression of PAX9 in a large group of patients with ovarian cancer treated with platinum compounds." (PMID 34454589, 2021). "At the translational level, PAX9 behaves as a predictor of chemotherapy response to platinum in patients with ovarian cancer." (PMID 34454589, 2021). "Because PAX9 mRNA and protein are expressed at an extremely low level in human ovarian tissue, it remains puzzling how and why PAX9 may play a critical role in ovarian cancer." (PMID 35628401, 2022). "PAX9 and FKBP1B are differentially methylated in cisplatin-resistant ovarian cancer cells." (PMID 34454589, 2021).
thymic carcinoma (2 papers, 2022 to 2023). Thymic carcinoma (TC) is a type of thymic epithelial neoplasm characterized by a high malignant potential. "As an essential gene for the development of the thymus and parathyroid, PAX9 may also play a role in thymoma and thymic carcinoma and parathyroid cancer." (PMID 35628401, 2022). "Additionally, the suppression of general thymic epithelium markers, represented by PAX9 and SIX1, was observed in thymic carcinomas." (PMID 38201543, 2023). "Additionally, we discovered that pan-thymic epithelium markers, exemplified by PAX9 and SIX1, were notably suppressed in thymic carcinomas, suggesting another distinctive feature of this tumor type." (PMID 38201543, 2023). "Additionally, the pan-thymic epithelium markers, exemplified by PAX9 and SIX1, were significantly suppressed in thymic carcinomas." (PMID 38201543, 2023). "Therefore, we investigated the correlation between methylation and mRNA expression status in the genes newly identified as activated or suppressed in thymic carcinomas, specifically HIPK2, HDAC9, NFATC1, PAX9, and SIX1 (the methylation status of FEZF2 was not available in the dataset)." (PMID 38201543, 2023).
Waardenburg syndrome (2 papers, 2020 to 2026). A disorder characterized by varying degrees of deafness and minor defects in structures arising from neural crest, including pigmentation anomalies of eyes, hair, and skin. "PAX3 is known as key player in cranial neural crest development and is associated with neural crest-related diseases like Waardenburg syndrome, while PAX9 initiates tooth development." (PMID 33271866, 2020). "Pathogenic variants in PAX genes underlie diverse congenital disorders such as aniridia (PAX6), renal coloboma syndrome (PAX2), otofaciocervical syndrome with immunodeficiency (PAX1), Waardenburg syndrome (PAX3), maturity-onset diabetes of the young (PAX4), and tooth agenesis (PAX9)." (PMID 41751498, 2026).
anodontia (1 paper, 2016). Anodontia is an extreme developmental dental anomaly characterized by the complete absence of all teeth. "We scanned another female with non-syndromic anodontia and her younger brother with the same gene mutations of the PAX9,MSX1,AXIN2 and EDA, but without developmental abnormalities in the dentition." (PMID 26759063, 2016).
Barrett esophagus (1 paper, 2015). Esophageal lesion lined with columnar metaplastic epithelium which is flat or villiform. "Previous studies also reported an association of Pax9 with esophageal diseases such as Barrett’s esophagus and ESCC." (PMID 26630178, 2015). "Pax9 is reportedly down-regulated in Barrett’s Esophagus, and in progressive loss in dysplastic and cancerous epithelium of the human esophagus." (PMID 26630178, 2015). "Our data showed that Pax9 knockdown in zebrafish impaired differentiation of ESQE, supporting an important role of Pax9 in the pathogenesis of Barrett’s esophagus and ESCC." (PMID 26630178, 2015).
bone marrow cancer (1 paper, 2022). "PAX9 is upregulated in three bone or bone marrow cancer types, T-cell acute lymphocytic leukemia, Ewing sarcoma, and osteosarcoma." (PMID 35628401, 2022).
colon carcinoma (1 paper, 2020). "The same pre-rRNA processing defect was also detected in human embryonic kidney (HEK293FT) and colon carcinoma (RKO) cells depleted of PAX9, indicating that PAX9’s role in ribosome biogenesis is conserved among diverse human cell lines." (PMID 32813698, 2020).
deafness (1 paper, 2020). An inherited or acquired condition characterized by the complete loss of the ability to hear from one or both ears. "For example, we have previously reported a mutation which led to deafness by a long-range cis effect on a nearby gene: the Slc25a21tm1a(KOMP)Wtsi targeted mutation causes raised ABR thresholds by reducing expression of the nearby gene Pax9." (PMID 31927188, 2020).
degenerative disc disease (1 paper, 2017). "Importantly, identification of Pax1 and Pax9 as regulators of critical IVD genes has implications in understanding certain forms of kyphoscoliosis that have been linked to human PAX1 and PAX9, as well as degenerative disc disease." (PMID 28011632, 2017).
esophageal squamous cell carcinoma (1 paper, 2022). Esophageal squamous cell carcinoma (ESCC) is a type of esophageal carcinoma (EC) that can affect any part of the esophagus, but is usually located in the upper or middle third. "PAX9 expression was either lost or significantly reduced in the majority of esophageal squamous cell carcinoma (ESCC) and squamous epithelial dysplasia (pre-cancerous lesion)." (PMID 35628401, 2022).
esophagus cancer (1 paper, 2021). "For example, PAX9 and TP73 appeared specifically in esophagus cancer." (PMID 34712617, 2021).
metastatic melanoma (1 paper, 2019). A melanoma that has spread from its primary site to another anatomic site. "So, we concluded that up-regulation of miR-450b and down-regulation of PAX9 and BMP4 were interconnected with the high MMP9 expression in metastatic melanoma cells." (PMID 31569419, 2019).
Obesity (1 paper, 2024). Accumulation of substantial excess body fat. "We highlighted the novel genes SLC25A21 and PAX9 on 14q13.3, also identified in the GWAS after adjusting for the BMI, supporting the notion that the genetic architecture of snoring was partly not explained by obesity." (PMID 38461358, 2024).
oral cancer (1 paper, 2020). "Previously, we found a set of retinoid signaling related genes, including ADHFE1, ALDH1A2, CRBP1, PAX9, GDF10, TGFBR3, and PPARγ were frequently hypermethylated and downregulated in OSCC patient samples, suggesting the severe molecular defects in RA metabolism in oral cancer." (PMID 32238162, 2020).
otitis media (1 paper, 2014). Inflammation of the anatomical structures of the middle ear, which is most often caused by an infectious process. "The phenotypes we observed in homozygous Slc25a21tm1a(KOMP)Wtsi mice were broadly consistent with a hypomorphic Pax9 allele with the exception of otitis media and hearing impairment which may be a novel consequence of Pax9 down regulation." (PMID 24642684, 2014).
scoliosis (1 paper, 2014). A congenital or acquired spinal deformity characterized by lateral curvature of the spine. "MO knockdown of either Pax1 or Pax9 causes defects in the neural arch and scoliosis and double knockdown revealed that Pax1 and Pax9 function synergistically in sclerotome development." (PMID 25197636, 2014).
sinus (1 paper, 2024). "The WNT signaling pathway, such as PAX9, is involved in developing 80% of epithelial-origin tumors in oral and maxillary sinus squamous cell cancers." (PMID 39337467, 2024).
small cell lung carcinoma (1 paper, 2022). Small cell lung cancer (SCLC) is a highly aggressive malignant neoplasm, accounting for 10-15% of lung cancer cases, characterized byrapid growth, and early metastasis. "Genome-wide CRISPR-Cas9 dropout screen in small cell lung cancer (SCLC) cells identified PAX9 as an essential factor that is overexpressed and is transcriptionally driven by the BAP1/ASXL3/BRD4 epigenetic axis." (PMID 35628401, 2022).
cancer (17 papers, 2010 to 2025). A tumor composed of atypical neoplastic, often pleomorphic cells that invade other tissues. "Conversely, activation of PAX9 is linked to enhanced drug sensitivity during chemotherapy, turning a focus on possible carcinoma therapeutics." (PMID 39337467, 2024). "Second, mutations at different sites of PAX9 can cause dental agenesis with different manifestations, including the location and number of missing teeth, as well as other conditions such as maxillofacial deformities and cancer." (PMID 40226363, 2025). "In LUAD patients, higher expression of PAX9 is associated with poorer prognosis and enhanced tumor progression, while in cell lines it regulates significantly reduces cell proliferation, migration, and invasion, suggesting its role in promoting aggressive cancer behavior." (PMID 40506992, 2025). "The predictive significance of PAX9 in pan-cancer was assessed utilizing the Kaplan-Meier Plotter website." (PMID 39819533, 2025). "PAX9 overexpression inhibited the cancer cell proliferation and promoted apoptosis through the upregulation of caspase-3, poly (ADP-ribose) polymerase, and BAX and the down-regulation of BCL2." (PMID 35628401, 2022). "Several mouse lines are available for studies on cancer development in vivo: Pax9 hypomorphic mouse, Pax9 knockout mouse, Pax9fl/fl mouse, Pax9CreER mouse, and Pax9Cre mouse." (PMID 35628401, 2022). "In conclusion, understanding the roles and molecular mechanisms of PAX9 in cancer development will be a fruitful research area." (PMID 35628401, 2022). "In oral SCC tissue samples, the methylation levels of both PAX9 transcripts were higher in cancer than in matched normal tissues." (PMID 35628401, 2022). "Genetic alterations (mutation, amplification, and deletion) of the PAX9 gene are relatively common in lung adenocarcinoma and squamous cell carcinoma (SCC) but rare in most other cancers." (PMID 35628401, 2022). "This review summarizes the current understanding of PAX9 expression and functions in various cancers, pathways regulating PAX9 expression, and its downstream target genes and pathways." (PMID 35628401, 2022). "Here, we review the current understanding of PAX9 expression, upstream regulation of PAX9, and PAX9 downstream events in cancer development." (PMID 35628401, 2022). "PAX9 mRNA is differentially expressed in several human cancers as compared to the corresponding normal tissues." (PMID 35628401, 2022). "The methylation rates for PAX9 were similar in the three cohorts, with the lowest value corresponding to the Spanish National Cancer Research Center (CNIO) group." (PMID 34454589, 2021). "UALCAN studied the methylation levels of PAX9 in pan-cancer." (PMID 39819533, 2025). "Although PAX9 is often called an oncogene or tumor suppressor gene in the literature, neither overexpression nor loss/mutation of PAX9 is sufficient to induce cancer." (PMID 35628401, 2022). "It remains unknown whether these molecular pathways or genes may regulate PAX9 expression in specific cancers." (PMID 35628401, 2022). "The available data suggest that overexpression or loss/mutation of PAX9 is unlikely to transform cells or induce cancer." (PMID 35628401, 2022). "Promoter methylation has been shown as a regulatory mechanism of PAX9 expression in cancer." (PMID 35628401, 2022). "Cellular and tissue contexts seem to be important for the functions of PAX9 in cancer development." (PMID 35628401, 2022). "The differential expression pattern of PAX9 in cancer and normal tissues may suggest its involvement in carcinogenesis." (PMID 35628401, 2022). "In consideration of its role in the development of multiple tissues and organs, PAX9 likely regulates cell proliferation and differentiation of specific cells and thus contributes to cancer development in specific cell and tissue contexts when being silenced, mutated, or overexpressed." (PMID 35628401, 2022). "To date, only one study has described the role of PAX9 as a predictive marker in cancer." (PMID 34454589, 2021).
cancer (continued). "It would be interesting to examine whether PAX9 upregulation may contribute to these cancers." (PMID 35628401, 2022). "The involvement of members from subgroup I (PAX1 and PAX9) and IV (PAX4 and PAX6) in cancer processes seem less significant." (PMID 40506992, 2025). "The promotion of cancer development is confirmed also in SCLC, where PAX9 acts as a key downstream target of the BAP1/ASXL3/BRD4 chromatin remodeling complex." (PMID 40506992, 2025). "Therefore, the role of PAX9 in cancer development is largely unknown." (PMID 35628401, 2022). "Interestingly, mutations in the AXIN2, MSX1, PAX9, and WNT10A genes may be associated with cancers." (PMID 34378652, 2021). "Reflecting the pleiotropic functions of the vitamin D/PTH axis, other potential candidate genes were also implicated immune/inflammatory processes (NKX2, PSMA6, SNX6) as well as cancer (NKX2, NKX3, PAX9)." (PMID 27579147, 2016). "They identified several genes (AXIN2, MSX1, PAX9, WNT10A, EDA, BARX, and BRCA1) that may play a role in both hypodontia and cancer development." (PMID 38523193, 2024). "Methylation of PAX9 and MSX1 have been associated with cancer development but have not been described the relation between this phenomenon and dental agenesis." (PMID 24316698, 2014).
tumor (11 papers, 2019 to 2025). "In multiple SCLC cell lines, PAX9 deletion significantly induced a primed-active enhancer transition and caused overexpression of many neural differentiation and tumor-suppressive genes." (PMID 35628401, 2022). "Genetic depletion or pharmacological inhibition of PAX9 can reactivate these enhancers, promoting tumor-suppressive pathways and neural differentiation." (PMID 40506992, 2025). "Mechanistically, PAX9 interacts with components of the nucleosome remodeling and deacetylase (NuRD) complex to block expression of tumor suppressor genes." (PMID 40506992, 2025). "Continuous expression of NKX2-8 and PAX9 was essential to the tumor maintenance of amplified SCC cells (H2170 cells)." (PMID 35628401, 2022). "In vivo experiments demonstrated that PAX9 overexpression reduced the tumor weight and volume, decreased proliferation, and increased apoptosis." (PMID 35628401, 2022). "Continuous expression of NKX2-8 and PAX9 may be essential to the tumor maintenance of amplified SCC cells, and both gene knockdown and overexpression experiments further supported oncogenic roles for these genes." (PMID 40506992, 2025). "In HNSCC, PAX9 is a potential tumor suppressor, inhibiting tumor invasion and migration." (PMID 39819533, 2025). "PAX9 is involved in early tumor development, modulates cellular function, and may induce carcinogenesis." (PMID 38511062, 2024). "Patients with hypomethylation of PAX9, STK33, GPR150, INSM1, and EPHX3 showed a shorter survival time and a higher tumor‐related mortality." (PMID 31131446, 2019). "Similarly, in a recent study on tumor-specific DNA methylation in ESCC cases from nine high-incidence countries, the top three prioritized genes (PAX9, SIM2, and THSD4) shared similar methylation differences in the discovery and replication sample sets." (PMID 35628401, 2022). "Interestingly, PAX1/PAX9 and their related group PAX4/PAX6 are believed to be neutral or tumor suppressors, whereas other Pax genes are believed to be oncogenic." (PMID 35628401, 2022). "Notably, several basal progenitor state factors (Hoxc13, Pax9, Gli2, Krt15) displayed paradoxical downregulation, indicating that EY-driven transcriptional changes do not reflect a physiologic OEPC cell state, but rather constitute a unique cellular state related to tumor initiation." (PMID 37961717, 2023).
PAX9 also shares sentences with these, for which no sentence is quoted: developmental delay (2 papers); genetic disorder (2); alveolar rhabdomyosarcoma (1); aniridia (1); brain-lung-thyroid syndrome (1); Choreoathetosis (1); dental anomalies (1); ectodermal dysplasia (1); esophageal diseases (1); Ewing sarcoma (1); facial cleft (1); head and neck squamous cell carcinoma (1); hypothyroidism (1); Immunodeficiency (1); Intellectual disability (1); Kyphoscoliosis (1); leukemia (1); maturity-onset diabetes (1); Microdontia (1); osteogenesis imperfecta (1); osteosarcoma (1); otofaciocervical syndrome (1); ovarian tumor (1); parathyroid cancer (1); renal coloboma syndrome (1); squamous cell carcinoma (1); T-cell acute lymphocytic leukemia (1); Thymic aplasia (1); thymoma (1).